DNMT3A (DNA methyltransferase 3 alpha)
Diseases named in the same sentence as DNMT3A in open-access papers (continued):
Sharing a sentence is not in itself a finding about the gene and the disease.
gastric cancer (continued). "Emerging studies found that the levels of DNMT1, DNMT3A, and DNMT3B mRNA are reportedly increased in various malignancies, including colorectal, liver, and gastric cancers." (PMID 19638978, 2009). "DNMT3A also down regulates p18INK4C (an important cell cycle regulator and inhibitor of CDK4/6-CyclinD complexes) in a methylation-dependent manner, which leads to increased cell proliferation in gastric cancer." (PMID 30376837, 2018). "Previously, we demonstrated that andrographolide suppresses the lytic reactivation of EBV in gastric cancer cell lines by attenuating the expression of host transcription factors, SP1 and MEF2, via epigenetic modifications, especially through the function of HDAC6 and DNMT3A." (PMID 37958849, 2023). "Our results also showed that hsa-miR-29c-5p is an important regulator of CDC42 and DNMT3A genes in the intestinal subtype gastric cancer and hsa-miR-135b-5p regulates the APC gene in both intestinal and diffuse subtypes of GC." (PMID 30376837, 2018). "We determined the DNMT3A genotype and CpG methylation status of 4 genes (p14ARF, p16INK4a, DAPK, and CDH1) in 510 subjects without gastric cancer." (PMID 33066747, 2020).
lymphoma (38 papers, 2013 to 2025). A malignant (clonal) proliferation of B- lymphocytes or T- lymphocytes which involves the lymph nodes, bone marrow and/or extranodal sites. "For example, mutations in TET2 and DNMT3A are frequently observed in CD4 + T-helper cell-derived lymphomas, such as angioimmunoblastic T-cell lymphoma." (PMID 41431105, 2025). "Up to 80% of patients with TFHL have underlying CH, with shared TET2 and/or DNMT3A mutations in the early progenitor cells (i.e., hematopoietic stem cells) as well as the lymphoma." (PMID 37500795, 2023). "To understand further molecular effects of monoallelic Dnmt3b loss on TCL development and the extent to which it resembles Dnmt3a-deficient lymphomas, we next analyzed gene expression in Dnmt3b+/− and Dnmt3aΔ/Δ TCLs by RNA-seq." (PMID 33450231, 2021). "Inactivation of the DNMT3B gene accelerated the development of lymphoma in DNMT3A-deficient mice, which indicates that the upregulation of DNMT3B inhibits disease progression in DNMT3A-deficient lymphoma." (PMID 32751889, 2020). "Though less frequently, DNMT3A mutations were also found in lymphomas." (PMID 36797244, 2023). "In some cases of lymphoma and MM, gene mutations in DNMT3A or TET2 were the only detected events." (PMID 33436578, 2021). "Thus, our analysis of methylomes identifies both specific and overlapping events associated with decreased Dnmt3b and Dnmt3a levels in mouse lymphomas." (PMID 33450231, 2021). "Fewer genes (252 overexpressed and 239 underexpressed) were shared between human PTCL and Dnmt3aΔ/Δ PTCL, suggesting that the transcriptome of lymphomas induced by loss of a single Dnmt3a allele more so resembles human disease than those that arise do to full inactivation of Dnmt3a." (PMID 27690235, 2016). "The recently detected DNMT3A mutation being reported by the French lymphoma study group in one single case of their series of CD4+ lymphoproliferation has hitherto not been described in PCFBCL, and thus might represent a discriminatory molecular feature if validated in further studies." (PMID 36358692, 2022). "Overall, DNMT3A mutations should be involved in clonal hematopoiesis, but it still remains unclear whether they are directly involved in the Tfh specification or differentiation in Tfh lymphomas." (PMID 32704161, 2020). "Interestingly, most DNMT3A mutations in Tfh lymphomas occur together with TET2 mutations." (PMID 32704161, 2020). "DNMT3A or TET2 gene mutations were detected in AML, lymphoma, or myeloma patients, with equal prevalence." (PMID 40869343, 2025). "Several studies have highlighted the characteristic mutational landscape of TFH lymphomas, which typically associates mutations in epigenetic regulators (TET2, DNMT3A, and IDH2), RHOA G17V, and alterations in the T-cell receptor (TCR) signaling pathway." (PMID 37500795, 2023). "TFH lymphomas frequently harbor TET2 and DNMT3A mutations, and identical mutations have been identified in both the malignant T-cells and the myeloid component of patients, suggesting a common ancestral clone with subsequent divergent evolution." (PMID 37646869, 2023). "Many studies have now established that up to 80% of patients with TFH lymphomas carry the same TET2 and/or DNMT3A mutations identified in the T-cells and the myeloid cells." (PMID 36793612, 2023). "As reported in other studies, the representative genetic alterations to induce a robust T follicular helper phenotype (RHOA, IDH2, and DNMT3A) of AITL also appeared in other TFH lymphomas." (PMID 33990228, 2021).
lymphoma (continued). "DNMT3A and TET2 mutations are often co-identified in clonal hematopoietic cells in Tfh lymphoma patients." (PMID 32704161, 2020). "Serial transplantation of Dnmt3a+/- lymphoma cells induced PTCL within 2 months in secondary and tertiary transplanted mice, illustrating their selective advantage to grow and induce disease." (PMID 27690235, 2016). "Lymphomas that develop in both Dnmt3aΔ/Δ and Dnmt3a+/- mice are exclusively CD8+CD4- mature T cell lymphomas." (PMID 27690235, 2016). "10% of Dnmt3a+/- mice develop lymphomas, suggesting that Dnmt3a is a haploinsufficient tumor suppressor in PTCL." (PMID 27690235, 2016). "NGS of the RMH lymphoma panel revealed multiple mutations in TET2 (n = 4) and DNMT3A (n = 1), which were identical in both LN specimens and microdissected CD8+ T cells, with similar VAFs, and these changes were confirmed by Fluidigm PCR/Illumina MiSeq sequencing." (PMID 35064935, 2022). "In the meantime, sequencing of non-lymphoma controls’ CSF cfDNA showed no mutation in five, insufficient cfDNA in two, and DNMT3A c.1851+1G>A mutation (VAF 0.9%) in one (CONTROL-5)." (PMID 36059608, 2022). "Interestingly, these loci were even more hypomethylated in Dnmt3bΔ/Δ; Dnmt3a+/−, and Dnmt3aΔ/Δ lymphomas we derived in our previous studies further suggesting interplay between Dnmt3b and Dnmt3a in their methylation functions." (PMID 33450231, 2021). "For instance, RIP-Seq analysis in lymphoma cells indicated that nuclear eIF4E binds over 3000 mRNAs that encode proteins acting in lymphoma-sustaining pathways such as B-cell receptor signaling (Bcl2, Bcl6) and DNA methylation/epigenetic regulation (DNMT1, DNMT3A, HDAC1)." (PMID 30455716, 2018). "Interestingly, transcriptomes of Dnmt3a+/- and Dnmt3aΔ/Δ lymphomas were largely conserved and significantly overlapped with those of human tumors." (PMID 27690235, 2016). "To date, DNMT3A mutations have been detected in AML, CML, CMML, MDS, lymphoma and MPN." (PMID 23946816, 2013). "There are five members in the DNMT family, including DNMT1, DNMT2, DNMT3a, DNMT3b, and DNMT3L, the most common mutation of DNMT in cancer is the DNMT3a mutation, while DNMT3b is a pro-carcinogenic gene in endometrial, lung and prostate cancer, and a tumor suppressor gene (TSG) in lymphoma." (PMID 38200495, 2024). "Furthermore, these lymphomas exhibit a congruent mutational spectrum, notably featuring loss-of-function mutations in genes associated with methylation, such as TET2, identified in approximately 80% of instances, and DNMT3A, observed in 30–40% of cases." (PMID 38365716, 2024). "There are a couple of notable findings: first, more than one CH clone can be present in the BM, and their clonal representations in the BM may not reflect those in the lymphoma, as seen in the DNMT3A-mutated clones in patient #4." (PMID 34581268, 2021). "However, two recent studies report frequencies of DNMT3A mutations in PTCL-NOS categorized as PTCL-NOS-GATA3 or PTCL-NOS-TBX21 as <15%, indicating aberrant accumulation of these mutations in Tfh lymphomas." (PMID 32704161, 2020). "Moreover, it has been reported that DNMT3A may directly inhibit the upregulation of DNMT3B in lymphoma in animal models." (PMID 32751889, 2020).
lymphoma (continued). "As expected from previous work, mice with Flt3ITD/+ alone developed MPN, while loss of one or both Dnmt3a alleles cooperates with the Flt3ITD mutation to elicit the development of an MPN or an acute leukemia of varying lineages including AML and T lymphoblastic leukemia /lymphoma (T-ALL)." (PMID 27636998, 2016). "Notably, mutations without specific clinical meanings might be detected in non-lymphoma patients, like low frequency DNMT3A splicing mutation." (PMID 36059608, 2022). "Mutations related to the RAS family (RHOA) and those related to epigenetic regulators (IDH2, DNMT3A, and TET2) were shown mainly in AITL and other TFH lymphomas." (PMID 33990228, 2021). "Comparison of gene expression patterns obtained from lymphomas to patterns obtained from normal CD8+ T cells revealed that Dnmt3aΔ/Δ and Dnmt3a+/- PTCLs shared strikingly similar expression profiles." (PMID 27690235, 2016). "Particularly, the low VAF of DNMT3A gene in cases #6 and #7, both patients without evidence of BM lymphoma involvement, is strongly suggestive of CH promoted by IBD." (PMID 35494055, 2022). "Notably, mutations related to the RAS family (RHOA) and those related to epigenetic regulators (IDH2, DNMT3A, and TET2) were found mainly in AITL and other TFH lymphomas." (PMID 33990228, 2021). "A combined analysis of global methylation and gene expression identified promoter hypomethylation as a major deregulated event in PTCL development in the absence of Dnmt3a with as many as 500 genes hypomethylated in lymphomas." (PMID 27690235, 2016). "In human lymphoma U-937 and RAJI cells, 14 displayed the highest antiproliferative and cell death inducing effects, consistently with the highest inhibitory potency showed against DNMT3A." (PMID 24810902, 2014). "Similarly, the mutational profile of FTCL seems to be similar to other nodal TFH lymphomas with mutations in TET2, DNMT3A, and RHOAG17V, but not in IDH2 which are usually restricted to AITL." (PMID 36793612, 2023). "Finally, in human lymphoma U-937 and RAJI cells, the N-(1-benzylpiperidin-4-yl)-2-(4-phenylpiperazin-1-yl)quinazolin-4-amine induced the highest proliferation arrest and cell death induction starting from 10 μM, in agreement with its DNMT3A inhibitory potency." (PMID 24810902, 2014). "Importantly, among Tfh lymphomas, IDH2R172 mutations are mostly confined to AITL and are rare in FTCL and PTCL-NOS with Tfh phenotype or GEP, unlike recurrent mutations in TET2, DNMT3A, and RHOA, which are common to all types of Tfh lymphomas." (PMID 32704161, 2020). "Unlike DNMT3A/B, DNMT1 levels did not seem to be changed in lymphomas (data not shown)." (PMID 38464090, 2024).
ovarian carcinoma (38 papers, 2012 to 2026). A malignant neoplasm originating from the surface ovarian epithelium. "Since DNMT3A suppressed the level of expression of the microRNA or enhanced the aerobic glycolysis process, cell proliferation, migration, and invasion of ovarian cancer, its overexpression was linked to miR-603." (PMID 40868085, 2025). "The overexpression of DNMT3A was associated with miR-603 as DNMT3A inhibited the expression of the microRNA and promoted aerobic glycolysis, cell proliferation, migration, and invasion of ovarian cancer." (PMID 37110218, 2023). "In conclusion, these results suggest that the loss of miR-199-3p expression in ovarian cancer is due to promoter hypermethylation which is enhanced by DNMT3A." (PMID 28743276, 2017). "This study aimed to determine aberrant expression of DNMT1, DNMT3a, and DNMT3b in benign and malignant ovarian tumor tissues for their association with clinicopathological significance and prognostic value." (PMID 22768205, 2012). "It has been suggested that knockdown of DNMT3A can attenuate the proliferation and invasiveness of ovarian cancer cells, but the impact of mutations in this respect is unknown." (PMID 38175731, 2024). "Here, we show in both high‐grade serous OVCA lines and a primary clear cell OVCA culture that VEGFA drives ovarian cancer stem‐like cell expansion via Src‐dependent upregulation of DNMT3A, leading to methylation‐dependent loss of miR‐128‐2 and Bmi1 upregulation." (PMID 28179359, 2017). "Some studies in solid tumours have reported that DNMT3a is upregulated in ovarian cancer, gastric adenocarcinoma, and bladder cancer and is associated with poor prognosis." (PMID 39990668, 2025). "In patient samples, and similarly to our results, the DNMT3A protein level was found to be elevated in ovarian cancer tissues compared to normal ovary tissues." (PMID 37894317, 2023). "Ginsenoside Rg3 has also been shown to increase the expression of tumor suppressor von Hippel-Lindau (VHL) gene in ovarian cancer cells via suppressing DNMT3A expression and thus downregulating the DNA methylation level of the VHL promoter." (PMID 34950039, 2021). "Rg3 upregulated miR-519a-5p via reducing DNMT3A-mediated DNA methylation to inhibit an HIF-1α-stimulated Warburg effect in ovarian cancer." (PMID 33477683, 2021). "We detected RNA levels of miR-145 and DNMT3A in 15 normal ovarian tissue samples and 31 ovarian cancer tissue samples." (PMID 33419459, 2021). "For example, miR-145 comprises the DNMT3A-miR-145-FSCN1 axis in ovarian cancer, and its downregulation by Rg3 inhibits EMT." (PMID 33477683, 2021). "In contrast to its action in hemopoietic malignancies, DNA methyl transferase 3A (DNMT3A) appears to play a pro‐oncogenic role in ovarian cancer." (PMID 28179359, 2017). "Several evidences showed that DNMT3A was highly expressed in various cancers including ovarian carcinoma." (PMID 28743276, 2017). "Considering that DNMT3A is primarily responsible for the 5mC maintenance, we examined the role of DNMT3A in the methylation of miR-199a promoter in ovarian cancer cells." (PMID 28743276, 2017). "In conclusion, we found that 20(S)-Rg3 reversed EMT to inhibit ovarian cancer cells migration and invasion via antagonizing DNMT3A-mediated methylation of pre-miR-145 to promote inhibition of miR-145 on FSCN1." (PMID 28881818, 2017). "The data showed that DNMT3a expression was higher in ovarian cancer than that in benign tumors, which was consistent with the previous studies in other types of cancer." (PMID 22768205, 2012). "The data showed that expression of DNMT1, DNMT3a, and DNMT3b was observed in 76 (53.5%), 92 (64.8%) and 79 (55.6%) of 142 cases of ovarian cancer tissues, respectively." (PMID 22768205, 2012).